RNU6-1328P (RNA, U6 small nuclear 1328, pseudogene)
Gene: Small nuclear RNA gene on chromosome 7 (94,495,299 to 94,495,404, forward strand). Ensembl gene ENSG00000222870.
Homologues: Orthologues: chimpanzee U6 (99% identical), macaque U6 (90% identical), mouse Gm25039 (73% identical), guinea pig U6 (60% identical). Paralogues in human: RNU6-744P (85% identical), RNU6-1209P (84% identical), RNU6-1091P (83% identical), RNU6-1309P (83% identical), RNU6-560P (83% identical), RNU6-834P (83% identical), RNU6-727P (82% identical), RNU6-742P (82% identical), RNU6-797P (82% identical), RNU6-1340P (81% identical), RNU6-21P (81% identical), RNU6-238P (81% identical), and 1285 more.